PIN1 (peptidylprolyl cis/trans isomerase, NIMA-interacting 1)
Diseases named in the same sentence as PIN1 in open-access papers (continued):
Sharing a sentence is not in itself a finding about the gene and the disease.
medulloblastoma (1 paper, 2018). A malignant, invasive embryonal neoplasm arising from the cerebellum. "A search for GLI1-binding proteins in medulloblastoma showed that GLI1 and PIN1 form a physical complex in MED-311FH medulloblastoma cells and that this interaction leads to increased GLI1 protein abundance in vitro." (PMID 30314361, 2018). "Based on this finding, Xu and colleagues investigated the consequence of PIN1 inhibition on SHH-medulloblastoma tumorigenesis in vivo." (PMID 30314361, 2018). "Recent work has provided evidence that implicates PIN1 in SHH-medulloblastoma." (PMID 30314361, 2018). "In turn, this possibility suggests that mechanisms involving interaction between GLI1 and PIN1 may represent potential therapeutic targets in SHH-driven medulloblastoma tumorigenesis." (PMID 30314361, 2018). "Using a genetically engineered SMO-induced mouse model of SHH-medulloblastoma, these authors demonstrated that PIN1 knockout in these mice has no detectable effect on normal cerebellar development but impairs tumor development and increases survival." (PMID 30314361, 2018).
memory impairment (1 paper, 2024). "Furthermore, cerebral ischemic insults activate DAPK1, which phosphorylates Pin1 Ser71 and leads to Pin1 inhibition, cis P-tau induction, pathology, neuroinflammation and memory impairment." (PMID 38628595, 2024).
Merkel cell carcinoma (1 paper, 2013). "Furthermore, although the expression of PIN1 is frequently observed in patients with Merkel cell carcinoma, those with a higher degree of PIN1 expression have been reported to have a significantly longer overall survival compared with those with a lower degree of expression." (PMID 24179535, 2013).
metastatic melanoma (1 paper, 2018). A melanoma that has spread from its primary site to another anatomic site. "Interestingly, cytoplasmic Pin1 expression was also significantly associated with poor survival of patients with metastatic melanoma." (PMID 30442923, 2018). "In the validation set TMA, the fraction of cells with high cytoplasmic Pin1 expression was increased in primary and metastatic melanoma compared with nevi (P = 0.046 and 0.011, respectively, χ2 test)." (PMID 30442923, 2018). "Furthermore, we investigated the correlation between Pin1 expression and patient survival in both primary and metastatic melanomas." (PMID 30442923, 2018). "In addition, nuclear Pin1 expression was not correlated with age or sex of metastatic melanoma patients." (PMID 30442923, 2018).
nematode infection (1 paper, 2009). "The pin1 loss-of-function mutation showed the highest effect on nematode reproduction, as nematode infection of pin1 mutants was reduced up to 40%." (PMID 19148279, 2009). "Reducing the PIN1-mediated auxin transport towards nematode infection sites resulted in a 40% reduction in number of cysts, indicating that almost half of the nematodes capable to infect did not succeed to initiate a NFS." (PMID 19148279, 2009). "To examine which PIN proteins might play a role in auxin distribution during NFS formation, we analyzed PIN expression during early nematode infection (2 and 5 dpi) using PIN1, 2, 3, 4, and PIN7::GUS transgenic plants." (PMID 19148279, 2009). "Since PIN1 expression is downregulated in NFS, this implicates that auxin transport from the shoot to the root tip is needed for an efficient nematode infection." (PMID 19148279, 2009).
Nephroblastoma (1 paper, 2024). An embryonal neoplasm characterized by the presence of epithelial, mesenchymal, and blastema components. "This discovery provides novel insights into the relationship between Pin1 and nephroblastoma tumor pathogenesis." (PMID 38711994, 2024).
ovarian tumor (1 paper, 2022). "The carried drug managed to alter Pin1 cancer-driving pathways by inducing proteasome-dependent degradation of Pin1, the delivery system as a whole proving to be an effective alternative for curbing ovarian tumor growth in vivo." (PMID 36015374, 2022).
overnutrition (1 paper, 2023). An imbalanced nutritional status resulting from excessive intake of nutrients. "However, the mechanism through which overnutrition and/or high-fat diet feeding induces Pin1 overexpression remains unclear, and is an important question awaiting resolution." (PMID 37240193, 2023).
periodontitis (1 paper, 2022). An acute or chronic inflammatory process that affects the tissues that surround and support the teeth. "Another protein, peptidyl-prolyl cis/trans isomerase NIMA-interacting 1 (PIN1), was upregulated in chronically inflamed human periodontal ligament cells in periodontitis patients." (PMID 35251010, 2022).
prostatic hyperplasia (1 paper, 2022). "In contrast, only prostatic hyperplasia and PIN1 or 2 lesions revealed in prostate tissues of age-matched Hi-Myc:ArL/Y:Gli1CreER/+ counterparts." (PMID 36323713, 2022). "In contrast, grafts derived from ARKO UGM with Ctnnb1L(ex3)/+:PBCre4 UGE showed mild pathological lesions resembling prostatic hyperplasia and PIN1." (PMID 36323713, 2022).
pulmonary diseases (1 paper, 2015). "Since Pin1 controls the mRNA stability of several cytokines and chemokines, it is also an attractive target for pulmonary diseases and diseases relating to the immune system, such as inflammation." (PMID 25992900, 2015).
Sepsis (1 paper, 2019). Sepsis is defined as life-threatening organ dysfunction caused by a dysregulated host response to infection. "Pharmacological targeting of Pin1 could be a valuable approach in sepsis." (PMID 31736979, 2019). "Targeting Pin1 could be a new approach to treat inflammation and sepsis." (PMID 31736979, 2019).
skin cancer (1 paper, 2024). "In skin cancer, the enzyme Pin1, which plays a role in protein folding and cell cycle control, is up-regulated, whereas the level of Pin1 is decreased in the brain of patients with AD." (PMID 38739932, 2024). "In skin cancer, the expression of Pin1 is increased, resulting in the prevention of Aβ- and tau-related pathology in the brain." (PMID 38739932, 2024).
squamous cell carcinoma (1 paper, 2014). A carcinoma arising from squamous epithelial cells. "Notably, a mis-activation of p63 in squamous cell carcinomas has been functionally linked with the activation of the FGFR2 receptor, further supporting the view that FGFs participate in Pin1-dependent p63 stability." (PMID 24569166, 2014).
T-cell leukemia (1 paper, 2016). A malignant disease of the T-lymphocytes in the bone marrow, thymus, and/or blood. "Overall, our findings provide new insights unveiling a possible dual mechanism focused on phosphorylation-dependent prolyl-isomerization by Pin1 as responsible for sustained Notch3-IC expression and signaling in T-cell leukemia." (PMID 26876201, 2016).
Telangiectasia (1 paper, 2020). Telangiectasias refer to small dilated blood vessels located near the surface of the skin or mucous membranes, measuring between 0.5 and 1 millimeter in diameter. "The significance of the phosphorylation-dependent Pin1 activity was recently highlighted for isomerization of ATR (ataxia telangiectasia- and Rad3-related)." (PMID 32426354, 2020).
temporal lobe epilepsy (1 paper, 2023). A localization-related (focal) form of epilepsy characterized by recurrent seizures that arise from foci within the temporal lobe, most commonly from its mesial aspect. "Pin1 is downregulated in the hippocampus and cortex of temporal lobe epilepsy (TLE) mouse models, which leads to an increase in N‐methyl‐d‐aspartate receptor complex formation, contributing to neuronal injury and apoptosis." (PMID 37990376, 2023).
theileriosis (1 paper, 2025). "The pin1 gene is highly conserved between T. annulata and T. parva (both of which cause transforming theileriosis), and the variations detected in the field samples are predominantly in positions that are conserved in the two species." (PMID 40679975, 2025).
thyroid (1 paper, 2011). "Our present results, which have focused on PIN1 mRNA expression, as well as our earlier data, concerning cyclin D1 mRNA overexpression in thyroid malignancy, may suggest that one of the major regulatory mechanisms in cell transformation in thyroid carcinogenesis is PIN1 gene activity." (PMID 21219594, 2011).
ulcerative colitis (1 paper, 2021). An inflammatory bowel disease involving the mucosal surface of the large intestine and rectum. "In this study, Peptidyl-prolyl cis-trans isomerase NIMA-interacting 1 (Pin1) protein was shown to be dramatically upregulated in the colons of dextran sodium sulfate (DSS)-induced ulcerative colitis model mice." (PMID 34067858, 2021).
cancer (261 papers, 2007 to 2026). A tumor composed of atypical neoplastic, often pleomorphic cells that invade other tissues. "In contrast, recent studies have highlighted the importance of NRF2 stabilization/activation by PIN1 in cancer progression, providing new insights into the underlying mechanisms." (PMID 40087364, 2025). "In CT26 mouse models, combining Pin1 inhibition with PD-1 blockade enhanced immunotherapy efficacy by reducing Treg infiltration, suppressing cancer-associated fibroblast (CAF) activity, and promoting CD8+ T cell recruitment." (PMID 41246306, 2025). "Dysregulation of PIN1 is associated with the development of various pathologies including cancer, obesity, diabetes, and inflammation." (PMID 40087364, 2025). "Dysregulation of Pin1 has been implicated in various diseases, including Alzheimer’s disease, aging-related disorders, and cancer." (PMID 40534867, 2025). "The oncogenic properties associated with dysregulation of Pin1 activities identify the isomerase as an attractive target for the development of new therapeutic approaches for cancer treatment." (PMID 38687676, 2024). "Despite these discoveries, our knowledge about the mechanisms underlying aberrant Pin1 expression in cancers remains very limited." (PMID 38167292, 2024). "Through modulating the conformation of the BRCA1-BARD1 complex, Pin1 is involved in the replication fork protections associated with cancer development." (PMID 38167292, 2024). "Considering that uncontrolled cell proliferation is a common hallmark of cancer, the inhibition of Pin1 holds the potential to simultaneously target multiple oncogenic signaling pathways at distinct levels." (PMID 38318109, 2024). "Carriers of the −842G>C SNP in the Pin1 promoter have been associated with decreased Pin1 expression levels and a decreased risk for cancer." (PMID 38745861, 2024). "Recent work has identified PIN1 polymorphisms to be of interest for suppressing formation of tau tangles, but contributing to cell proliferation in cancer." (PMID 39324538, 2024). "Pin1 in tumor cells and cancer-associated fibroblasts (CAFs) functions to constitute an immunosuppressive microenvironment to facilitate tumor growth." (PMID 38167292, 2024). "In particular, overexpression of Pin1 has been linked with tumorigenesis in several types of cancer." (PMID 37508437, 2023). "In a number of other cancer types, cytoplasmic localisation of PIN1 has been associated with cancer aggressiveness and poor prognosis." (PMID 36707636, 2023). "Peptidyl-prolyl isomerase (Pin1) regulates the activity and stability of many cancer-associated target proteins." (PMID 38020885, 2023). "Pin1 is commonly overexpressed or hyperactivated in diverse human cancer types, and its expression is commonly associated with poor patient prognoses." (PMID 38020885, 2023). "PIN1 is an oncoprotein that is often associated with cancer and PIN1’s function is defined by its two domains: the WW domain and the PPIase domain." (PMID 37370134, 2023). "Despite its clear and essential role in normal neuronal function, global pharmacologic manipulation of Pin1 carries risk as a variety of malignant tumors overexpress Pin1." (PMID 37849016, 2023). "There are 32 somatic mutations reported in the Pin1 gene among different types of cancer suggesting a correlation between Pin1 mutation and the increased risk of cancer." (PMID 37508437, 2023).
cancer (continued). "In a number of other cancer types, PIN1 overexpression and cytoplasmic localisation of PIN1 has been associated with cancer aggressiveness and metastasis." (PMID 36707636, 2023). "Pharmacological inhibition of the prolyl isomerase PIN1, highly expressed in cancer cells and cancer associated fibroblasts (CAF), has been proposed for cancer therapy." (PMID 35879297, 2022). "Single nucleotide polymorphisms (SNPs) in the promoter region of the Pin1 gene that inhibit Pin1 expression are associated with increased AD risk and decreased cancer risk." (PMID 36199128, 2022). "Many studies have indicated that Pin1 overexpression is significantly correlated with poor cancer prognoses, the underlying mechanism of which is associated with the promotion of cancer cell proliferation and migration by Pin1." (PMID 35461311, 2022). "Humans with genetic polymorphisms associated with reduced isomerase PIN1 expression are at a lower risk of cancer, whereas PIN1 overexpression is associated with increased risk of proliferative diseases." (PMID 36619302, 2022). "Overall, Pin1 drives tumor progression and is negatively associated with clinical outcome in patients with cancer 19-21." (PMID 33537091, 2021). "Pin1 is associated with the development of various cancers and is therefore regarded as a molecular timer of the cell cycle." (PMID 33807199, 2021). "The genetic variant −842G>C in the promoter region of PIN1 gene is associated with increased risks of cancer and decreased risks of AD." (PMID 34733188, 2021). "In this review, we summarize the underlying mechanisms of Pin1-mediated upregulation of oncogenes and downregulation of tumor suppressors in cancer development." (PMID 33807199, 2021). "The authors perceived that cancers with overexpression of Pin1 (such as lung or ovarian) were associates with decreased prevalence of neurodegenerative diseases such as AD." (PMID 34523079, 2021). "Although cumulative results suggest that Pin1 is strongly associated with cell proliferation and cancer development, Pin1 has been shown to have a tumor suppressor function." (PMID 32195254, 2020). "Since the discovery of juglone as the first Pin1 inhibitor in 1998, diverse Pin1 inhibitors were developed to treat Pin1-associated cancers or probe Pin1 biology." (PMID 33024085, 2020). "Considering that Pin1 has also been reported to have a tumor suppressing function, Pin1-directed inhibitors must be carefully implicated in cancers." (PMID 31884567, 2020). "Pin1 is a member of the peptidylprolyl isomerase (PPIase) family that has been reported to be overexpressed in many cancers and is associated with a poor prognosis." (PMID 32010480, 2020). "Several studies have reported that some single nucleotide polymorphisms (SNPs) of the Pin1 gene increases the cancer risk, whereas other variants function as protective factors." (PMID 32258027, 2020). "Aberrant expression of Pin1 has been identified to be associated with many diseases, especially in cancer and neurodegenerative disorders, such as Parkinson’s disease (PD) and Alzheimer’s disease (AD)." (PMID 32266261, 2020). "The deregulation of Pin1 expression and/or activity is associated with the development of cancer and neurodegeneration, including AD." (PMID 32500074, 2020). "In cancer—one of the leading causes of human death worldwide —Pin1 is widely overexpressed and/or overactivated compared with normal cells or tissues." (PMID 32296699, 2020). "Intriguingly, PIN1 is widely overexpressed in many human cancers and is associated with poor clinical outcomes." (PMID 30789902, 2019). "For example, the up-regulation of Pin1 activity leads to various cancers, on the contrary, it causes Alzheimer’s disease." (PMID 31182777, 2019). "Deregulated Pin1 function has been implicated in various diseases, and Pin1 is being investigated as a potential therapeutic target in cancer and immune disorders." (PMID 31349602, 2019).